BNIP3 (BCL2 interacting protein 3)
Diseases named in the same sentence as BNIP3 in open-access papers (continued):
Sharing a sentence is not in itself a finding about the gene and the disease.
renal fibrosis (continued). "The deletion of BNIP3 decreased the activity of MnSOD, increased mitochondrial ROS and activated the NLRP3 inflammasome and renal fibrosis following UUO." (PMID 36928344, 2023). "HIF1α-BNIP3-mediated mitophagy protected RTECs against hypoxia and renal tissue following UUO by decreasing mitochondrial ROS and inhibiting activation of the NLRP3 inflammasome to attenuate renal fibrosis." (PMID 36928344, 2023). "Since Bnip3 is a well‐known player of hypoxia‐induced apoptosis and Snail and TGF‐β1 are the key regulators of epithelial to mesenchymal transition and renal fibrosis, the activation of HIF‐1α‐regulated pathways could mediate renal damage." (PMID 30614190, 2019). "However, in UUO mice and hypoxia-induced HK-2 cells, knockdown of BNIP3 aggravated mitochondrial structural damage, decreased mitophagy and increased mtROS expression, which further enhanced NLRP3-mediated inflammation and aggravated renal fibrosis after UUO." (PMID 38680884, 2024).
lymph node metastasis (8 papers, 2009 to 2024). "BNIP-3 negativity was associated with capsular invasion in FC (p = 0.001), and p62 negativity was associated with lymph node metastasis in MC (p = 0.006)." (PMID 28257096, 2017). "Tumors which showed loss of expression of BNIP3 had significantly more often lymph node metastases (82% vs 39%, p = 0.010) and showed a higher mitotic activity index (p = 0.027)." (PMID 19505343, 2009). "Conversely, in patients with renal cell carcinomas Bnip3 expression is correlated with lymph node metastasis." (PMID 31921862, 2019). "This study indicates that lymph-node metastasis, BNIP3 expression and TGM2 expression are independent prognostic factors in laryngeal SCC patients receiving postoperative radiotherapy." (PMID 22458929, 2012). "Primary tumor site, T stage, overall stage, lymph-node metastasis, BNIP3 expression and TGM2 expression were significant prognostic factors for OS in univariate analysis." (PMID 22458929, 2012). "However, our study found for the first time that methylation of RHOF, CRMP1, BNIP3 and HOXA5 promoters is associated with lymph node metastasis." (PMID 36454866, 2022). "Downregulation of Bnip3 is characteristic of lymph node metastases in breast cancer." (PMID 31921862, 2019). "The univariate analysis indicated that patients with lymph node metastasis (P=0.001), clinical stage II (P=0.001) and BNIP3 negative expression (P=0.002) were significantly associated with an increased risk of cancer-related death." (PMID 28968982, 2017). "By examining the relationship between BNIP3 expression and clinicopathological features, we found a highly significant inverse correlation between BNIP3 expression and presence of lymph node metastases, both on the protein level and mRNA level, this in contrast to a previous study." (PMID 19505343, 2009). "However, methylation of RHOF, CRMP1, BNIP3 and HOXA5 promoters has not been reported to be associated with lymph node metastasis, and our study is the first to find that methylation of these gene promoters is associated with lymph node metastasis." (PMID 36454866, 2022).
non-small cell lung carcinoma (8 papers, 2009 to 2026). A group of at least three distinct histological types of lung cancer, including non-small cell squamous cell carcinoma, adenocarcinoma, and large cell carcinoma. "The increased expression of Bcl-2/adenovirus E1B 19kDa-interacting protein 3 (BNIP3), a stress sensor protein, is associated with autophagy, dissemination, and poor prognosis in the early stages of non-small-cell lung cancer (NSCLC)." (PMID 36614301, 2023). "On the other hand, increased levels of BNIP3 protein have been described in non-small cell lung cancer, where high expression of BNIP3 protein was linked with a poor prognosis." (PMID 19505343, 2009). "Abnormal increases in BNIP3 expression are affected by HIF-1 expression, which is positively correlated with tumor metastasis in non-small cell lung cancer." (PMID 29632473, 2018).
renal carcinoma (8 papers, 2017 to 2025). A carcinoma arising from the epithelium of the renal parenchyma or the renal pelvis. "Subsequently, by knocking down Bnip3, Cav-1, or Gsn in renal cancer/renal progenitor cell hybrid organoid models, the research team further validated the roles of these genes in renal organogenesis and renal cell carcinoma development." (PMID 39600908, 2024). "There are some basic experimental studies on the biological function of two target genes (RRM2 and BNIP3) regulated by FRlncRNAs for renal cancer." (PMID 35350243, 2022). "BNIP3 expression is suppressed by histone deacetylation in renal carcinoma and hematopoietic tumors." (PMID 33207677, 2020). "Studies in renal carcinomas have demonstrated that BNIP3 expression correlates positively to HIF-1α activity, but negatively to HIF-2α suggesting distinct roles in apoptotic signaling as well." (PMID 29045486, 2017). "Our data indicate that in renal carcinoma cells, Bnip3 acts as an anti-apoptotic factor." (PMID 29084770, 2017). "Von Hippel-Lindau protein defectiveness (e.g., in the RCC4 renal carcinoma cell line) results in constitutive HIF-1α expression and subsequent BNIP3 overexpression." (PMID 33207677, 2020).
renal cell carcinoma (8 papers, 2018 to 2025). "Previous investigations have established that PSME2 overexpression facilitates renal cell carcinoma progression via BNIP3-mediated autophagic regulation." (PMID 41211066, 2025). "Initially, we investigated the protein expression of BNIP3 and HIF-1α in renal cell carcinoma cell lines A498, 786-O, CAKI-1, ACHN, and GRC." (PMID 40837014, 2025). "On this basis, the expression of BNIP3 protein and mRNA in renal cell carcinoma cell lines A498, 786-O, CAKI-1, ACHN, and GRC was analyzed, and A498 and 786-O cells with lower expression were selected to be transfected with BNIP3 overexpression plasmid to construct overexpressing BNIP3." (PMID 40837014, 2025).
sarcopenia (8 papers, 2022 to 2025). Progressive decline in muscle mass due to aging which results in decreased functional capacity of muscles. "Decreased expression of muscle BNIP3 induces accelerated ageing and muscle atrophy, which are associated with the development of sarcopenia, compared to high levels of BNIP3 in aged subjects." (PMID 38553412, 2024). "Notably the human brain, similar to skeletal muscle, shrinks during aging; therefore, BNIP3 could be a target in sarcopenia if it reduces a loss of mass due to the maintenance of mitochondrial populations." (PMID 38030595, 2024). "Importantly, when stratifying aged subjects into low and high BNIP3 expressers, we detected a clear association between BNIP3, inflammation and the probability of developing sarcopenia and other comorbidities, as measured by the Charlson comorbidity index (CCI)." (PMID 40396050, 2022). "Dysregulation of this pathway upregulates muscle degradation markers (e.g., MuRF1, Atrogin-1, and Bnip3) while suppressing protein synthesis, contributing to the pathogenesis of sarcopenia." (PMID 41171716, 2025). "In certain organs such as healthy muscles, although expressed continuously, BNIP3 shows an increased expression during aging as a process to mitigate inflammation and prevent sarcopenia." (PMID 40848274, 2025). "In such a condition, BNIP3 downregulation further exacerbated mitochondrial damage and contributed to muscle atrophy, suggesting that in chronic aging sarcopenia, increased BNIP3 represents an adaptive response aimed at removing damaged mitochondria." (PMID 39766033, 2024). "In general, decreased levels of mitophagy markers such as PINK1, parkin BNIP3, NIX, PHB2, FUNDC1, and AMBRA1 are associated with a reduced quality of life in sarcopenia associated with aging." (PMID 36561214, 2022). "On the basis of our results, interventions enhancing BNIP3‐regulated mitochondrial health emerge as a promising strategy to prevent muscle inflammaging and sarcopenia." (PMID 35263007, 2022). "This notion was confirmed by the finding that aged subjects with low muscle BNIP3 expression present worsened muscle aging characterized by increased inflammation and likelihood of developing sarcopenia." (PMID 40396050, 2022). "Past literature shows that in skeletal muscle BNIP3 levels actually increased in aging, so it remains unclear if this increase may serve as a protective mechanism against sarcopenia." (PMID 38030595, 2024). "In addition, reduced levels of mitophagy markers such as PINK1, Parkin, BNIP3, NIX, PHB2, FUNDC1, and AMBRA1 negatively impact sarcopenia-related muscle weakness and the quality of life in the elderly." (PMID 36561214, 2022).
triple-negative breast carcinoma (8 papers, 2016 to 2025). An invasive breast carcinoma which is negative for expression of estrogen receptor (ER), progesterone receptor (PR), and human epidermal growth factor receptor 2 (HER2). "To this end, we used MDA-MB-231 cells, a triple-negative breast cancer cell line that prominently expresses BNIP3." (PMID 38177312, 2024). "The closely related BNIP3 had been shown to act like a tumor suppressor in triple negative breast cancers." (PMID 37190124, 2023). "HER2-positive and triple-negative breast cancers seemed to have an increased proportion of BNIP3-positive cancer cells as compared with ER-positive breast cancers." (PMID 35912211, 2022). "BNIP3 deletion in triple-negative breast cancer promoted the metastasis of disease by deregulating mitophagy." (PMID 35912211, 2022). "The correlation between BNIP3 and tumor progression/metastasis formation is investigated in triple negative breast cancer where BNIP3 null tumor cells enhanced ROS formation that, in turn, led to HIF1 alpha activation and invasive phenotype." (PMID 31210843, 2019). "Here we utilized a triple-negative breast cancer cell line, MDA-MB-231, that forms dense hypoxic tumors in vivo to study the posttranslational regulation of BNIP3 in hypoxic and nonhypoxic conditions." (PMID 38177312, 2024).
cervical cancer (7 papers, 2013 to 2024). A primary or metastatic malignant neoplasm involving the cervix. "Cervical cancer patients with high BNIP3 expression in the TCGA cohort had a significantly decreased overall survival as compared with those with low BNIP3 expression." (PMID 35912211, 2022). "As expected, CQ enhanced MAC-induced apoptosis of cervical carcinoma cells, and this effect was caused by the accumulation of LC3 and BNIP-3." (PMID 36499465, 2022). "Next, we investigated BNIP3 expression in a cervical cancer single-cell atlas." (PMID 35912211, 2022). "BNIP3-positive cervical cancer cells displayed a shifted transcriptional signature." (PMID 35912211, 2022). "As expected, MAC increased HIF-1α and BNIP-3 expression in cervical carcinoma cells." (PMID 36499465, 2022). "Among the transcription factors activating BNIP3 expression the most characterized is HIF1α, which attracted our attention because it is also known for promoting glycolysis and proliferation of cervical cancer cells." (PMID 33706793, 2021). "Collectively, these results demonstrate that the CQ-mediated increase in LC3II, p62, and BNIP-3 expression promotes MAC-induced apoptosis and leads to cell death in cervical carcinoma cells." (PMID 36499465, 2022). "In conclusion, our study demonstrated that induced BNIP-3 expression by MAC directly promotes apoptosis and autophagy and lead to cell death in cervical carcinoma cells." (PMID 36499465, 2022). "In this study, we demonstrated the importance of BNIP-3 in the relationship between MAC-induced apoptosis and autophagy and proposed a strategy for inducing autophagy in cervical cancer cells using MAC that could have therapeutic implications." (PMID 36499465, 2022).
Hyperglycemia (7 papers, 2015 to 2026). An increased concentration of glucose in the blood. "Treatment of HG cardiomyocytes with EVs derived from ticagrelor pretreated- H9c2 cells resulted in the inhibition of the expression of autophagy markers Beclin and Bnip3, which are drastically upregulated depending on the hyperglycemia." (PMID 35383227, 2022). "Similarly, while Pgam5 deletion maintained the transcription of Parkin, Fundc1, and Bnip3, this effect was abrogated by Phb2 siRNA in hyperglycemia-treated cardiomyocytes." (PMID 38818468, 2024). "MET exerted protective effect against hyperglycemia-induced endothelial impairment, which was contributed to MET improving HG-inhibited GLI1 activity and BNIP3 expression in HUVECs." (PMID 33162888, 2020). "LC3II/LC3I ratio was significantly decreased due to acute hyperglycemia, however, other autophagy-related proteins such as Beclin-1, total and Triton X-100-insoluble SQSTM1/p62, phospho-ULK1 (Ser555), ATG7 and BNIP3 were unchanged in AHG group." (PMID 26581389, 2015).
liver cancer (7 papers, 2014 to 2025). An epithelial or non-epithelial malignant neoplasm that arises from the liver. "Our results have demonstrated that CD24, a “don’t eat me” signal, has been upregulated in liver cancer organoids together with BNIP3." (PMID 35912211, 2022). "In liver cancer cells, BNIP3 was proposed to be a therapeutic target for cancer metastasis as BNIP3 upregulation enhanced anoikis resistance of HCC cells." (PMID 35912211, 2022). "We further validated the upregulation of BNIP3 in liver cancer 3D organoid cultures compared with 2D culture." (PMID 35912211, 2022). "Our study suggested that BNIP3 might be involved in the enhanced tumorigenicity of liver cancer cells." (PMID 35912211, 2022). "BNIP3 is highly expressed in liver cancer cells, and activates autophagy to delay cell death." (PMID 36675706, 2022). "Previously it was reported that treatment of mouse primary hepatocytes with peroxisomes proliferators (including Wy14643) for 24 hours led to upregulation of 11 genes related to liver cancer (i.e. Angptl4, Bnip3, Dbi, Fabp1, Fabp2, Fasn, HifIa, Lgals3, Ly6d, Mgll, SerpineI)." (PMID 25511156, 2014). "To analyze the roles of NIX and BNIP3 in apoptin-induced autophagy, we analyzed the inhibitory effect of apoptin on liver cancer cells after NIX and BNIP3 were silenced and autophagy inhibited." (PMID 36050738, 2022).
cardiac hypertrophy (6 papers, 2015 to 2025). "Given that BNIP3 is also involved in other cellular processes such as inflammation, apoptosis, and necrosis, BNIP3‐mediated mitophagy could be an epiphenomenon associated with cardiac hypertrophy progression." (PMID 35845350, 2022). "Several studies have shown that the downregulation of PINK1 and BNIP3/NIX in a genetic intervention model induces pathological cardiac hypertrophy and cardiomegaly." (PMID 39335620, 2024). "The potential role of BNIP3 and/or VEGFα in cardiac hypertrophy induced directly or indirectly by maternal fructose intake deserves further research." (PMID 39335874, 2024). "Intriguingly, BNIP3, a key player involved in Parkin‐independent mitophagy, appears to accelerate the progression of cardiac hypertrophy." (PMID 35845350, 2022). "Further study is necessary to determine whether BNIP3‐mediated mitophagy is a compensatory mechanism to sustain the heart function in the course of cardiac hypertrophy." (PMID 35845350, 2022). "Another report demonstrated that Bnip3 bound and sequestered Rheb in HEK 293 cells; therefore we hypothesized that Bnip3 sequestration of Rheb may prevent ventricular hypertrophy in Bnip3-TG mice." (PMID 26317696, 2015).
dilated cardiomyopathy (6 papers, 2013 to 2024). Cardiomyopathy which is characterized by dilation and contractile dysfunction of the left and right ventricles. "In conclusion, we have shown that Bnip3 activates p300 and associated acetylation reactions to levels that were shown previously to cause maladaptive hypertrophy and dilated cardiomyopathy." (PMID 26317696, 2015). "For example, loss of Bnip3 has recently been correlated with dilated cardiomyopathy and impaired mitophagy via unknown mechanisms." (PMID 38203804, 2024). "Our studies using Bnip3 overexpressing transgenic mice confirm a previous report that cardiac-specific overexpression of Bnip3 results in progressive contractile dysfunction and dilated cardiomyopathy (DCM)." (PMID 26317696, 2015). "Our data suggested that Bmal1 ablation reduced BNIP3 expression and impaired normal mitochondrial quality control process, which might gradually induced abnormal cardiomyocyte function and phenotypes of dilated cardiomyopathy." (PMID 32277346, 2020).
Hepatic steatosis (6 papers, 2019 to 2025). Steatosis is a term used to denote lipid accumulation within hepatocytes. "In addition, BNIP3 was overexpressed both in vitro and in vivo to validate the role of L-Phe in BNIP3-mediated mitophagy associated with liver steatosis." (PMID 40588730, 2025). "Based on these findings, it is inferred that liver steatosis caused by L-Phe could be related to BNIP3-mediated mitophagy." (PMID 40588730, 2025). "The relationship between mitophagy and hepatic steatosis was first observed in an earlier study showing that the expression of BNIP3, a mitophagy receptor, is induced by fasting and that loss of BNIP3 triggers hepatic steatosis and promotes its transition into steatohepatitis in mice." (PMID 32235615, 2020). "Additionally, loss of BNIP3 was shown to result in reduced mitochondrial integrity and increased lipogenesis in the livers of BNIP3-null mice, suggesting the critical role of mitophagy in regulating normal liver metabolism and preventing hepatic steatosis." (PMID 32235615, 2020). "In summary, we discovered a novel function of L-Phe in the body: downregulating BNIP3-mediated mitophagy and subsequently promoting liver steatosis." (PMID 40588730, 2025). "We further conducted rescue experiments by overexpressing BNIP3, a key protein involved in mitophagy, both in vivo and in vitro to evaluate liver steatosis and mitophagy." (PMID 40588730, 2025). "The mechanism by which L-Phe promotes liver steatosis is through the inhibition of BNIP3-mediated mitophagy, as shown in our findings." (PMID 40588730, 2025). "Our study revealed the role of L-Phe in regulating lipid metabolism and promoting liver steatosis via BNIP3-mediated mitophagy." (PMID 40588730, 2025). "Our observations emphasize the importance of Hif-2α in promoting the progression of liver steatosis by functioning as a negative regulator of hepatic fatty acid β-oxidation and BNIP3-dependent mitophagy." (PMID 36476627, 2022). "BNIP3 overexpression effectively mitigated L-Phe-induced hepatic steatosis by restoring mitophagy." (PMID 40588730, 2025). "Given the acknowledged role of BNIP3-mediated mitophagy in liver protection, we investigated whether L-Phe regulates BNIP3-mediated mitophagy in the context of liver steatosis." (PMID 40588730, 2025). "We further investigated whether BNIP3-mediated mitophagy is involved in L-Phe-induced liver steatosis." (PMID 40588730, 2025). "We speculated that BNIP3-mediated mitophagy mediates the pathological process of liver steatosis." (PMID 40588730, 2025). "Moreover, L-Phe regulates the BNIP3-mediated PPARα and AMPK/mTOR signalling pathways to promote hepatic steatosis." (PMID 40588730, 2025). "Recent study has shown that BNIP3-, NIX-, and FUNDC1-mediated mitophagy plays a critical role in the treatment of lipid metabolism, hepatocellular carcinoma, hepatic insulin resistance, alcoholic liver disease, hepatic steatosis, and liver injury." (PMID 31649547, 2019).